MIR626 (microRNA 626)
Synonyms: hsa-mir-626; MIRN626
Gene: MicroRNA gene on chromosome 15 (41,691,585 to 41,691,678, forward strand). Ensembl gene ENSG00000207766.
Gene Ontology:
Biological process: miRNA-mediated post-transcriptional gene silencing
Cellular component: RISC complex
Homologues: Orthologues: chimpanzee ptr-mir-626 (100% identical), macaque mml-mir-626 (90% identical).